RN7SL117P (RNA, 7SL, cytoplasmic 117, pseudogene)
Gene: Miscellaneous RNA gene on chromosome 2 (21,922,993 to 21,923,288, forward strand). Ensembl gene ENSG00000264192.
Homologues: Orthologues: chimpanzee Metazoa_SRP (99% identical), macaque Metazoa_SRP (94% identical). Paralogues in human: RN7SL1 (80% identical), RN7SL3 (80% identical), RN7SL2 (79% identical), RN7SL113P (78% identical), RN7SL220P (77% identical), RN7SL828P (77% identical), RN7SL408P (77% identical), RN7SL559P (77% identical), RN7SL575P (77% identical), RN7SL664P (77% identical), RN7SL88P (76% identical), RN7SL44P (76% identical), and 702 more.